ADA (adenosine deaminase)
Diseases named in the same sentence as ADA in open-access papers (continued):
Sharing a sentence is not in itself a finding about the gene and the disease.
tumor (86 papers, 1979 to 2026). "Dpp4, the gene encoding the CD26 receptor that is necessary for adenosine deaminase activity, was upregulated in Ptger4-KO and Ptges-KO tumor cells." (PMID 39298269, 2024). "Seven tumor antigens (ADA, FYN, HDC, NFKBIZ, RASSF4, SLC6A3, and UPP1) associated with inferior prognoses and higher-level infiltration of antigen-presenting cells in PRAD were identified, thus promising candidates for mRNA vaccine." (PMID 35547260, 2022). "Altered ADA activity is thought to be associated with various kinds of tumours." (PMID 38556542, 2024). "PEGADA2 effectively suppress tumor growth and influence immune responses within the tumor microenvironment by targeting ADA activity." (PMID 41573544, 2025). "In hosts treated with an adenosine deaminase inhibitor, Ptger4-KO tumor cells accumulated adenosine and gave rise to tumors." (PMID 39298269, 2024). "Although these markers had not been previously shown as prognostic in HL, there is literature showing ADA and its ligand CD26 as higher in ALK-positive NHL and HL as well as being associated with poor outcomes in other tumor types." (PMID 38934093, 2024). "Our microarray analysis also showed overexpression of ADA mRNA in tumor tissues compared to normal tissues, which is consistent with the observations of other researchers." (PMID 39267843, 2024). "BMI, tumor type, ADA level, lactate dehydrogenase (LDH) level, and baseline TSH level differed between the thyroid irAEs and no thyroid irAEs groups, demonstrating that the baseline status of these indicators affected the occurrence of thyroid irAEs." (PMID 38774877, 2024). "More evidence of an interconnection of Ado in chronic inflammation and tumor growth can be derived from a study in humans suffering from a genetic defect in the Ado inactivating enzyme Adenosine Deaminase (ADA)." (PMID 38022572, 2023). "ADA is a key enzyme that protects T cells from adenosine inhibition, and its absence would promote tumor progression." (PMID 36969232, 2023). "The potency of immune response is further reinforced by reducing the accumulation of adenosine in tumor microenvironment by the activated ADA." (PMID 36727824, 2023). "Elevated ADA levels have already been described in the serum of PDAC patients correlating with tumor size and metastases." (PMID 36230528, 2022). "To further assess the importance of ADA in modulating the effects of cordycepin on tumor growth, we used siRNA targeting ADA on ADA-low (92.1) and ADA-high (MP46) lines." (PMID 35804893, 2022). "ADA can be examined as a target in anti-tumor therapy due to immune-modulating properties and the ability to limit the concentration of adenosine." (PMID 35327609, 2022). "Several studies have shown the change of ADA activities in serum and tumor tissues of breast cancer patients." (PMID 35663977, 2022). "The importance of ADA levels in predicting the response of a broad range of tumor cell lines to cordycepin suggested a combination therapy approach." (PMID 35804893, 2022). "Beginning on day three after tumor inoculation, gels containing 0.2 mg of aPD1 and 0.2 mg of ADA (aPD1/ADA gel) were injected subcutaneously around the tumor inoculation site for three doses, with each given 3 days apart." (PMID 36132332, 2022). "Prior studies in infectious organisms, and a very limited number of tumor types, suggested that ADA also recognizes 3′-deoxyadenosine/cordycepin and converts it to 3′-deoxy-inosine, inhibiting its therapeutic effects." (PMID 35804893, 2022). "The results suggest that peritumoral injection of aPD1/ADA gel skewed the T cell response in the dLN towards a tumor-rejecting phenotype." (PMID 36132332, 2022). "In this study, a larger number of the patients with TBP or PC were retrospectively enrolled, and then differentiating value of combined ascitic tumor markers and ADA were determined." (PMID 36115972, 2022).
tumor (continued). "Tumors from mice that received aPD1/ADA gel demonstrated higher gene expressions of tumor suppressor components compared to those which received saline." (PMID 36132332, 2022). "The biologics, aPD1, or aPD1 with adenosine deaminase (aPD1/ADA), were formulated with the self-assembling peptides Z15_EAK to enhance retention near the tumor inoculation site." (PMID 36132332, 2022). "First, we find that the anticancer effects of cordycepin alone are only seen in tumor cell lines with low ADA expression or activity." (PMID 35804893, 2022). "Treatment with aPD1/ADA gel rendered delayed tumor growth relative to in mice treated with saline, aPD1/ADA solution, and aPD1 gel." (PMID 36132332, 2022). "We postulated that the inhibitory effects of aPD1/ADA gel on tumor growth early in the process would enable tumor regression in the long term." (PMID 36132332, 2022). "This, together with the decrease in colony formation capacity, suggest that ADA treatment would not only decrease cell invasion, but also tumor aggressiveness bringing about a new therapeutic strategy for this deadly disease." (PMID 31671624, 2019). "Administration of B(a)P caused significant elevation in the activities of tumor markers such as AHH, ADA and LDH." (PMID 31842482, 2019). "Recently, another contribution of ADA inhibition in the suppression of tumor progression has been highlighted." (PMID 30441833, 2018). "Low‐dose dCF treatment protected against pathological response of the endothelium by the inhibition of adenosine deaminase activity measured in vascular and tumour tissues by about 70%." (PMID 30291675, 2018). "The inhibition of adenosine deaminase activity by dCF reduced tumour size that was closely related to the decreased aggressiveness of tumour cells by adenosine receptor‐dependent mechanisms and endothelial protection." (PMID 30291675, 2018). "Few studies on the diagnostic potential of cardiac Troponin I in viral acute pericarditis, pericardial fluid adenosine deaminase for tuberculous RP and classical tumor markers like CEA for neoplastic RP were published." (PMID 26909604, 2016). "We have shown that ecto-ADA plays a role in the auto-regulation of CD26/DPPIV in that it permits increased down-regulation of CD26/DPPIV due to adenosine in the hypoxic tumour environment." (PMID 26552750, 2015). "Clearance of adenosine by ADA can enhance immune surveillance, a process that is inhibited by the accumulation of adenosine in the tumor." (PMID 26552750, 2015). "The intracellular adenosine deaminase activities (ADA) in 12 different experimental animal tumours were measured." (PMID 508578, 1979). "However, some studies have reported that low ADA activity can promote tumour progression in head and neck tumours." (PMID 38556542, 2024). "The network connections of ADA suggest its role in modulating the tumor microenvironment, potentially affecting immune response and cell survival; modulating ADA activity could influence tumor progression and response to therapy." (PMID 39267843, 2024). "Additionally, a positive correlation was identified between L. eligens abundance and serum ADA concentration, assessing liver function and potentially influencing tumour development through adenosine degradation." (PMID 39620486, 2024). "Additionally, ADA is linked to RGS4 and LYN, highlighting its role in purine metabolism and immune response modulation in the tumor microenvironment." (PMID 39267843, 2024). "However, we believe that our study is the first to test cordycepin in combination with ADA inhibitors in a broad range of tumor cell lines." (PMID 35804893, 2022). "Moreover, in an explorative response prediction model, the combination of protein markers (CXCL9, CXCL10, IL-15, CASP8, and ADA) resulted in higher accuracy in predicting response than tumor PD-L1 expression or each protein assayed individually." (PMID 34206510, 2021).
tumor (continued). "For this reason, to ensure a massive release of ADA within the TME by non-professional cells (tumor cells), we also encoded an engineered ADA gene endowed with an ectopic signal peptide." (PMID 34948316, 2021). "However, this must to be tested by in vivo assays, evaluating the effect of ADA under a heterogeneous context as the tumor microenvironment." (PMID 31671624, 2019). "The results revealed that the oral administration of benzo(a)pyrene resulted in increases in relative lung weight, serum levels of tumor markers (ADA, AHH, and LDH), and the inflammatory marker NF-κB, and a decreased total antioxidant capacity compared with the control." (PMID 31660294, 2019). "It has been proposed that high ADA activity in tumour microenvironment may be a compensatory mechanism against a toxic accumulation of its substrates due to increased purine and pyrimidine metabolism in cancerous tissues." (PMID 30291675, 2018). "Thus, the application of ADK and ADA can become a perspective approach to anti-tumor therapy." (PMID 35327609, 2022). "Patients with a previous neoplasia or with symptoms such as weight loss, absence of fever, and low ADA levels in the PF were more often associated with MPE than with BPE in this study, and this agrees with previous reports of associations in patients with MPE2,3." (PMID 32231227, 2020). "Furthermore, we demonstrate that the addition of ADA is capable of decreasing colony formation in soft agar assays in PC-GSCs, demonstrating an effective method to decrease in vitro tumorigenicity of these cells responsible for tumor recurrence." (PMID 31671624, 2019). "Similarly, dCF decreased about 60% of total adenosine deaminase activity in tumour homogenates." (PMID 30291675, 2018). "The immunosuppressive effects of DCs can be alleviated by ADA, which converts the abundant ADO present at the tumor site into inosine." (PMID 40110052, 2025). "The substantial elevation in ADA, GGT, 5′-NT (CD73), and LDH following BaP exposure reflects tumor progression and metabolic alterations, which were effectively counteracted by 6-G-Lip administration." (PMID 40284009, 2025). "The results showed that the ADO level in the PPMAD(+) group was lower than that in the other groups, indicating that ADA effectively degraded ADO, thereby improving the tumor microenvironment." (PMID 40110052, 2025). "It focuses on enzymes involved in the metabolism of adenosine-ADK and ADA and provides an overview of biological significance of ADK and ADA and their role in the development of tumor." (PMID 35327609, 2022). "We found that aPD1/ADA gel increased CD8+ T cells and IFNɣ in tumors and decreased CD4+FoxP3+ regulatory T cells (Tregs) in tumor draining lymph nodes." (PMID 36132332, 2022). "In this current study we illustrated that ascitic tumor makers had high specificity and accuracy in differential diagnosis of PC from TBP; and ascitic ADA was also a good discriminator in these patients." (PMID 36115972, 2022). "Serum levels of tumor marker enzymes AHH, ADA and LDH and the inflammatory mediator NF-κB increased, while total antioxidant capacity (TAC) decreased." (PMID 31842482, 2019). "There have been a limited number of studies on the use of cardiac Troponin I (cTnI) in diagnosing viral acute pericarditis, adenosine deaminase (ADA) in pericardial fluid for tubercular pericarditis, and classical serum tumour markers like Carcinoembryonic Antigen (CEA) for neoplastic pericarditis." (PMID 39798014, 2025). "NPMCA could specifically release ADA via scissoring ROS‐cleavable linkers by the generated ·OH and 1O2 through CDT and SDT effect upon US treatment in the presence of H2O2 in tumor microenvironment, which leads to interference of adenosine metabolism." (PMID 36727824, 2023).
tumor (continued). "Only in the concurrence of the acidic TME and sono-irradiation, the nano-immunocomplex not only generates singlet oxygen (1O2) to eliminate tumor cells and induce ICD for improved tumor immunogenicity but also unleashes aPD-L1 and ADA via the scission of imine and thioketal bonds." (PMID 35710545, 2022). "After 2 days, 4T1 tumor-bearing mice were injected with mixed proteins (aPD-L1 and ADA), HNP, PNP, or HPNP and treated with or without sono-irradiation." (PMID 35710545, 2022). "In addition to NDPK, several other ectoenzymes mediate purine metabolism and homeostasis in the tumor microenvironment, including CD39, CD73, adenosine deaminase, and adenylate kinase." (PMID 33435297, 2021). "Adenosine is irreversibly deamidated to inosine by the adenosine deaminase (ADA) enzyme, while extra-cellular adenosine binds to adenosine receptors differently expressed by stromal and immune cells surrounding tumor, thus contributing to immune cell dysfunction." (PMID 32760402, 2020). "Reduction in ADA activity could reflect the ability of LLE to reduce purine turnover, and hence the tumor proliferation rate." (PMID 31842482, 2019). "Both H. pylori-exposed gastric epithelial cells and the tumor biopsies demonstrated significant up-regulation of five common genes (IL-8, CLDN1, KRT17, CLDN7 and MMP7) and down-regulation of four common genes (GPER, KIAA1324, ADA and SLC9A2)." (PMID 24321518, 2013). "However, higher ADA is not specific, as MPE can also exhibit moderately higher ADA due to increased lymphocyte turnover in the tumor microenvironment and by the tumor cells themselves, thus decreasing its specificity for TPE." (PMID 41399654, 2026). "In addition to the commonly used tumor marker CEA, our study also incorporated conventional biochemical parameters for serous effusion analysis—LDH and ADA—as previous studies have reported their potential utility in identifying malignant effusions and providing prognostic information." (PMID 41431643, 2025). "Additionally, the overexpression of ADA and SLC23A2 in tumor tissues suggests that these genes could be interesting therapeutic targets." (PMID 39267843, 2024). "In the tumor microenvironment with ultrasound (US) irradiation, NPMCA mediates CDT and SDT concurrently in deep tumors covered with 2‐cm tissues to produce abundant ROS, which results in dual‐cascade scissoring of ROS‐cleavable linkers to activate ADA within NCMCA to block adenosine metabolism." (PMID 36727824, 2023). "Other host-related factors such as disease state, tumor burden, and presence of ADA may impact on mAbs PK and were not included in this analysis." (PMID 37631343, 2023). "The effects of ADA and Z15_EAK were limited to tumor growth delay and lymph node enlargement." (PMID 36132332, 2022). "We therefore surmise that ADA treatment may reduce immunosuppressive adenosine in TME while increasing the levels of inosine to fuel tumour infiltrated T cells, thereby improving anti-tumour immunity." (PMID 32694789, 2020). "Unlike pentostatin, another ADA inhibitor erythro-9-(2-hydroxy-3-nonyl) adenine (EHNA) can induce the apoptosis of malignant pleural mesothelioma (MPM), which is an aggressive tumor that does not have effective therapy." (PMID 35327609, 2022).
infection (78 papers, 2006 to 2026). The state of being infected such as from the introduction of a foreign agent such as serum, vaccine, antigenic substance or organism. "It will be necessary, however, to follow these changes throughout a longer course of infection to substantiate a causal link between glycogen accumulation and truncated-ADA protein production during MAP infection." (PMID 27102525, 2016). "Absence of cellular and humoral immunity and a rapidly fatal course due to infections with fungal, viral, and opportunistic agents are characteristic of early onset forms of ADA deficiency." (PMID 22969765, 2012). "As a result of severely defected cellular and humoral immunity, the typical presentation of ADA-deficiency occurs early in life with severe infections and failure to thrive, and affected individuals will normally succumb within the first or second year of life without intervention." (PMID 29690908, 2018). "A prediction of the hypothesis that EAD is responsible for the protective effect of ADA inhibition is that inhibition of adenosine production should enhance susceptibility to infection." (PMID 26313746, 2015). "The biomarkers associated with an acute infection (Hp, albumin, PON-1 and ADA) are related to previously reported molecular biomarkers in the testicular parenchyma of infected bulls and could help in the diagnosis of early infections and complement IgM detection." (PMID 34551803, 2021). "The STP group and 66.7% of the PT group continued to maintain satisfactory levels of both ADA and dAXP with stable rates of infections and hospitalizations and stable lymphocyte counts for up to 48.6 months." (PMID 40140214, 2025). "A previous study of a shorter duration (8-10 weeks) demonstrated infection of hu-mice with a different set of viral strains, namely ADA (subtype B) and C1157 (African subtype C)." (PMID 40308596, 2025). "The infection commencement of ADA-SCID is earlier than other forms of SCID, but all forms have approximately the same symptoms." (PMID 39844821, 2025). "Rooted in an inherited gene defect, the condition hampers adenosine deaminase synthesis, leading to toxic deoxyadenosine accumulation that detrimentally affects infection‐fighting lymphocytes." (PMID 39245805, 2024). "In this study, aldolase and PCT, as well as ADA, were higher in the saliva of pigs with the infection compared to healthy pigs." (PMID 37525237, 2023). "Specifically, we isolated CD4+ T cells from HIV-1 uninfected, deidentified donor PBMCs and activated them with phytohemagglutinin (PHA) and IL-2 for 3 days before infection via spinoculation with HIV ADA." (PMID 36125890, 2022). "Haptoglobin, albumin, PON-1 and ADA were identified as the most promising biomarkers for the acute phase of the infection." (PMID 34551803, 2021). "Future studies should characterize ADA concentrations in the premature population in relation to immunologic parameters and infection to provide further insight into the functional consequences of ADA expression in early life." (PMID 34122398, 2021). "We found that EBV infection of NP-TERT cells resulted in a large (>10 fold) increase in ADA by days 4 and 7 post-infection." (PMID 33497421, 2021). "Upon infection of these cell lines with NL 4-3 ADA WT HIV-1, we observed downregulation of CD47 by 40% on JC47-hCD47 cells, but we observed a downregulation of only 10% on those expressing the chimeric JC47-cCD47." (PMID 34425695, 2021). "Haptoglobin, albumin, PON-1 and ADA were identified as the biomarkers that showed changes of higher magnitude in the acute phase of the infection, whereas high total protein and globulin values were found in chronically infected cattle." (PMID 34551803, 2021). "In this study, we determined the impact of four uncharacterized infection-responsive proteins in SG infection, i.e., ADA, SGS1, GILT-like and SGBAP." (PMID 34880409, 2021).